ANAPC2 (anaphase promoting complex subunit 2)
Description:
Component of the anaphase promoting complex/cyclosome (APC/C), a cell cycle-regulated E3 ubiquitin ligase that controls progression through the cell cycle. Together with the RING-H2 protein ANAPC11, forms the catalytic component of the E3 ubiquitin ligase complex. APC/C acts by mediating ubiquitination and subsequent degradation of target proteins: it mainly mediates the formation of 'Lys-11'-linked polyubiquitin chains and, to a lower extent, the formation of 'Lys-48'- and 'Lys-63'-linked polyubiquitin chains. APC/C catalyzes assembly of branched 'Lys-11'-/'Lys-48'-linked branched ubiquitin chains on target proteins. APC/C is activated by CDC20 in the metaphase/anaphase transition of cell cycle, targeting the degradation of cyclin B and securin. APC/C is regulated by the mitotic checkpoint complex (MCC), which inhibits APC/C and delays chromosome segregation. The CDC20-APC/C complex positively regulates the formation of synaptic vesicle clustering at active zone to the presynaptic membrane in postmitotic neurons (By similarity). CDC20-APC/C-induced degradation of NEUROD2 drives presynaptic differentiation (By similarity).
Synonyms: APC2; KIAA1406
Tractability: PROTAC: ubiquitination databases record sites on it; its protein half-life has been measured.
Gene: Protein-coding gene on chromosome 9 (137,174,784 to 137,189,028, reverse strand). Ensembl gene ENSG00000176248.
Subcellular location (Human Protein Atlas): Nucleoplasm; Mitochondria
Pathways (Reactome):
Cell Cycle: APC-Cdc20 mediated degradation of Nek2A; APC/C:Cdc20 mediated degradation of Cyclin B; APC/C:Cdc20 mediated degradation of Securin; APC/C:Cdc20 mediated degradation of mitotic proteins; APC/C:Cdh1 mediated degradation of Cdc20 and other APC/C:Cdh1 targeted proteins in late mitosis/early G1; Autodegradation of Cdh1 by Cdh1:APC/C; Cdc20:Phospho-APC/C mediated degradation of Cyclin A; Conversion from APC/C:Cdc20 to APC/C:Cdh1 in late anaphase; Inactivation of APC/C via direct inhibition of the APC/C complex; Phosphorylation of the APC/C; Regulation of APC/C activators between G1/S and early anaphase; Separation of Sister Chromatids
DNA Replication: Assembly of the pre-replicative complex; CDK-mediated phosphorylation and removal of Cdc6
Cellular responses to stimuli: Senescence-Associated Secretory Phenotype (SASP)
Disease: Aberrant regulation of mitotic exit in cancer due to RB1 defects
Gene expression (Transcription): Transcriptional Regulation by VENTX
Immune System: Antigen processing: Ubiquitination & Proteasome degradation
Gene Ontology:
Molecular function: protein binding
Biological process: anaphase-promoting complex-dependent catabolic process; protein branched polyubiquitination; protein K11-linked ubiquitination; protein K48-linked ubiquitination; metaphase/anaphase transition of mitotic cell cycle; positive regulation of synapse maturation; positive regulation of synaptic plasticity; regulation of meiotic cell cycle; regulation of mitotic cell cycle; negative regulation of gene expression; positive regulation of axon extension; positive regulation of dendrite morphogenesis; proteasome-mediated ubiquitin-dependent protein catabolic process; protein ubiquitination
Cellular component: anaphase-promoting complex; nucleoplasm; cytosol; cullin-RING ubiquitin ligase complex
Genetic constraint (gnomAD): Loss-of-function variants: 29 observed, 81.95 expected, observed/expected ratio (o/e) 0.35, 90% interval 0.26 to 0.48. The upper end of that interval is the gene's LOEUF score, 0.48, which puts it in group 2 of 6, group 1 being the genes least tolerant of losing a copy. Missense variants: 857 observed, 1,135.3 expected, observed/expected ratio (o/e) 0.75, 90% interval 0.71 to 0.8. Synonymous variants: 571 observed, 487.31 expected, observed/expected ratio (o/e) 1.17, 90% interval 1.09 to 1.26.
Homologues: Orthologues: chimpanzee ANAPC2 (99% identical), macaque ANAPC2 (99% identical), guinea pig ANAPC2 (95% identical), rat Anapc2 (95% identical), mouse Anapc2 (94% identical), dog ANAPC2 (93% identical), pig ANAPC2 (93% identical), tropical clawed frog anapc2 (66% identical), zebrafish anapc2 (53% identical), Drosophila melanogaster mr (35% identical), Caenorhabditis elegans apc-2 (21% identical). Paralogues in human: CUL4B (19% identical), CUL4A (18% identical), CUL3 (15% identical), CUL1 (14% identical), CUL5 (13% identical), CUL2 (12% identical), CACUL1 (7% identical).
Diseases named in the same sentence as ANAPC2 in open-access papers:
ANAPC2 is named in the same sentence as 11 diseases in open-access papers, as found by Europe PMC text mining. Sharing a sentence is not in itself a finding about the gene and the disease. The quoted sentences say what the papers report.
aplastic anemia (1 paper, 2017). Anemia resulting from bone marrow failure (aplastic or hypoplastic bone marrow). "We further studied the alteration of Anapc2 in the bone marrow (BM) failure disease, aplastic anemia (AA)." (PMID 28968996, 2017). "CD34+ cells were markedly decreased in the bone marrow and Anapc2-expression in the residual CD34+ cells was undetectable, suggesting that APC/C was deficient and might have a relationship with the pathogenesis of aplastic anemia." (PMID 28968996, 2017). "We next detected Anapc2-expression in the CD34+ HSPCs of patients with aplastic anemia." (PMID 28968996, 2017).
colon cancer (1 paper, 2023). "ANAPC2 was upregulated by artesunate and degraded the KRAS protein in colon cancer cells, so ANAPC2 may play an important role in pancreatic cancer in a similar manner." (PMID 38304253, 2023).
colorectal cancer (1 paper, 2023). A primary or metastatic malignant neoplasm that affects the colon or rectum. "In addition, E3 ligases anaphase-promoting complex subunit 2 (ANAPC2) promotes KRAS degradation through the ubiquitin–proteasome pathway in colorectal cancer." (PMID 36694209, 2023).
Ewing sarcoma (1 paper, 2013). A small round cell tumor that lacks morphologic, immunohistochemical, and electron microscopic evidence of neuroectodermal differentiation. "Among these, several necessary connections between ubiquitin proteasome system members (CUL1, SKP1, SKP2, ANAPC2) and EWS-FLI1 were identified, potentially indicating an interesting link between this oncogene and the protein turnover regulation in the context of Ewing sarcoma." (PMID 23935076, 2013).
HCMV infection (1 paper, 2018). "We report that ANAPC2, in addition to ANAPC1, 4, and 5, is degraded early during HCMV infection, suggesting that inhibition of these proteins may be of particular importance in subverting the host cell-cycle machinery during infection." (PMID 30122656, 2018).
tuberculosis (1 paper, 2022). A chronic, recurrent infection caused by the bacterium Mycobacterium tuberculosis. "Rv0222, which is a serodiagnostic protein for tuberculosis, was associated with anaphase promoting complex subunit 2 (ANAPC2) and promoted K11-linked-ubiquitination in K76 of Rv0222." (PMID 35572598, 2022).
infection (3 papers, 2008 to 2024). The state of being infected such as from the introduction of a foreign agent such as serum, vaccine, antigenic substance or organism. "NN1172-infection leads to the down-regulation of many genes related to cell cycle and DNA replication genes, including MCM 2 ~ 6, CDK1 ~ 2, CCNB2, ANAPC2, MAD2L1, WEE1, RBL1, RB1." (PMID 38362295, 2024).
tumor (2 papers, 2014 to 2022). "IHC assay was utilized for the levels of KRAS, β-TrCP, GSK-3β or ANAPC2 in tumor tissues." (PMID 35305671, 2022). "Interestingly, the partners of ANAPC2, CDC20 and CDH1, were also upregulated in this tumor, and APC/C has a recently-documented important role in cancer, and can be inhibited with a small molecule (Tosyl-L-Arginine Methyl Ester)." (PMID 25155515, 2014).
ANAPC2 also shares sentences with these, for which no sentence is quoted: and Muscular Disorder (1 paper); cancer (1); pancreatic cancer (1).